SOCS1 (suppressor of cytokine signaling 1)
Diseases named in the same sentence as SOCS1 in open-access papers (continued):
Sharing a sentence is not in itself a finding about the gene and the disease.
active tuberculosis (2 papers, 2013 to 2017). "Our results showed that active tuberculosis subjects had higher levels of SOCS-3 mRNA, lower expressions of SOCS-2, -4, -5, -6, -7, and cytokine-inducible SH2-containing protein-1 (CIS-1) mRNAs, but not SOCS-1 mRNA than healthy and LTBI subjects." (PMID 28430824, 2017).
acute gastritis (2 papers, 2020 to 2025). "In particular, we aim to collect gastric biopsy specimens from acute gastritis patients and assess miR-155/SOCS1 expression patterns, as well as explore relevant public datasets to evaluate clinical correlations." (PMID 41286271, 2025). "The absence of human correlative datasets (e.g., miR-155/SOCS1 expression profiles in acute gastritis patients) limits direct extrapolation of our findings to clinical settings." (PMID 41286271, 2025). "We show that H. pylori positive gastritis patients express significantly higher SOCS3, but not SOCS1 and SOCS2, levels compared to H. pylori negative patients." (PMID 33023610, 2020).
acute leukemia (2 papers, 2018 to 2021). A clonal (malignant) hematopoietic disorder with an acute onset, affecting the bone marrow and the peripheral blood. "A phase I trial demonstrates the safety and efficacy of SOCS1-silenced DCs in treating relapsed acute leukemia." (PMID 29415891, 2018).
anaphylaxis (2 papers, 2017 to 2018). An acute hypersensitivity reaction that occurs from exposure to an allergen. "The BALB/C mouse model of passive cutaneous anaphylaxis (PCA) was employed to investigate the role of SOCS1 in anaphylaxis." (PMID 28968979, 2017). "Roles of TGaseII, SOCS1, COX-2, and HDAC3 in allergic inflammation, such as anaphylaxis, have been previously reported." (PMID 30459600, 2018). "The role of SOCS1 in allergic inflammation, such as anaphylaxis has not been investigated." (PMID 28968979, 2017).
anaplastic large cell lymphoma (2 papers, 2014 to 2019). Anaplastic large cell lymphoma (ALCL) is a rare and aggressive peripheral T-cell non-Hodgkin lymphoma, belonging to the group of CD30-positive lymphoproliferative disorders, which affects lymph nodes and extranodal sites. "Persistent expression of SOCS1 and/or SOCS3 is observed in several haematological malignancies such as cutaneous T cell lymphoma (CTCL), chronic myeloid leukemia (CML), ALK+ anaplastic large cell lymphoma (ALCL), and some acute leukemia." (PMID 24757565, 2014).
anemia (2 papers, 2018 to 2021). A reduction in the number of red blood cells, the amount of hemoglobin, and/or the volume of packed red blood cells. "One prior report demonstrated that AMPK may interact with SOCS1 by inducing JAK2 degradation in anemia-induced inflammation." (PMID 30213073, 2018).
breast tumor (2 papers, 2018 to 2023). "SOCS1, originally recognized as a tumor suppressor, has been found to be overexpressed in various cancer types, including human breast tumors, epidermal tumors, neuronal tumors, and other cancer cells." (PMID 37720228, 2023).
Cachexia (2 papers, 2021 to 2022). Severe weight loss, wasting of muscle, loss of appetite, and general debility related to a chronic disease. "Promotes tumor progression, invasion, and migration andmediates apoptosis.Higher miR-155 contributes to cachexia through the inhibition of negative feedback loops of SOCS1.miR-155 mediates TNF-Α showing a pro-inflammatory effect." (PMID 36465353, 2022). "Regarding the NSCL cancer patients, significantly lower serum levels of SOCS1 and Foxp3 were noted in cachexia as compared with non-cachexia." (PMID 34900737, 2021).
cardiac hypertrophy (2 papers, 2016 to 2022). "The loss of miR-155 protects the heart from pathological cardiac hypertrophy and failure by targeting the suppressor of cytokine signaling 1 (Socs1)." (PMID 35269399, 2022).
Cerebral ischemia (2 papers, 2020 to 2023). Restriction of arterial blood supply to the brain associated with insufficient oxygenation to support the metabolic requirements of the tissue. "MiR-155 is capable of inducing the expression of TNF-α and IL-1β in cerebral ischemia by regulating TLR4 activity, consequently suppressing the expression of inflammatory mediators viz., suppressor of cytokine signaling 1 (SOCS1) and myeloid differentiation primary response protein 88 (MyD88)." (PMID 32937836, 2020).
cholestasis (2 papers, 2017 to 2023). Impairment of the bile flow caused by obstruction within the liver, or outside the liver in the bile duct system. "GW4064 treatment in the PNAC mouse increased hepatic FXR binding to the Stat3 promoter, further increased STAT3 phosphorylation and upregulated Socs1 and Socs3 mRNA, and prevented cholestasis." (PMID 36848082, 2023). "Although it cannot be ruled out that SOCS3 had a similar function as SOCS1, the unrecovered status of cholestasis provides a possible explanation." (PMID 28842621, 2017).
Chronic colitis (2 papers, 2014 to 2023). A chronic inflammatory disease of the large intestine (colon, cecum and rectum). "Recently, SCP has been shown to alleviate DSS-induced chronic colitis in mice by alleviating gut microbial dysbiosis and modulating the miR-155/SOCS1 axis." (PMID 38004208, 2023).
common variable immunodeficiency (2 papers, 2021 to 2024). "Here, we describe the first Argentinian patient presenting with common variable immunodeficiency and granulomatous–lymphocytic interstitial lung disease, harboring two in cis heterozygous variants in the SOCS1 gene." (PMID 39005503, 2024).
coronary heart disease (2 papers, 2017 to 2024). "Clinical significance of SOCS1 gene polymorphism in patients with coronary heart disease has been reported." (PMID 28915645, 2017). "miR-19a/b can effectively inhibit IAV replication by targeting and reducing the expression of SOCS1, as observed in cell-based and coronary heart disease mouse models." (PMID 38435118, 2024). "The SOCS1 gene participates in the development of coronary heart disease." (PMID 28915645, 2017).
Depression (2 papers, 2020 to 2022). "In future research, we would try to assess the related signal pathways regulated by miR‐345‐5p/SOCS1 in further studies to expand and facilitate the understanding of the roles of miR‐345‐5p in depression." (PMID 32730696, 2020). "Therefore, it was speculated that miR‐345‐5p may regulate the progression of depression through SOCS1." (PMID 32730696, 2020).
ductal carcinomas (2 papers, 2003 to 2018). "We report elevated expression of SOCS-1–3 and CIS immunoreactive proteins within in situ ductal carcinomas and infiltrating ductal carcinomas relative to normal breast tissue." (PMID 12888825, 2003).
enteropathies (2 papers, 2020 to 2023). "SOCS1 haploinsufficiency can result in a broad spectrum of intestinal manifestations and need to be considered as differential diagnosis in cases of severe treatment-refractory enteropathies, including the rare condition of lymphocytic leiomyositis." (PMID 37156989, 2023).
enteropathy-associated T-cell lymphoma (2 papers, 2021 to 2024). An uncommon mature T-cell lymphoma of intraepithelial lymphocytes. "SOCS1 has also been found to be mutated in malignancies involving other lymphoid malignancies, including T cell prolymphocytic leukemia (T-PLL), NK/T cell lymphoma, enteropathy-associated T cell lymphoma (EATL), as well as mycosis fungoides, a cutaneous T cell lymphoma (CTCL)." (PMID 34604264, 2021).
esophageal cancer (2 papers, 2021 to 2022). A primary or metastatic malignant neoplasm involving the esophagus. "For example, a study of 83 patients with esophageal cancer found that exosome-associated miR-19b-3p promotes tumor progression by inhibiting SOCS1 expression." (PMID 34527677, 2021). "In contrast, the BMMSC exosomal miR-19b-3p promotes esophageal cancer cell proliferation, migration, and invasion via targeting SOCS1." (PMID 35511336, 2022).
fibrosis (2 papers, 2019 to 2020). the formation of excess fibrous connective tissue in an organ or tissue in a reparative or reactive process. "TIMP1 and TIMP4 were both found to correlate inversely with suppressor of cytokine signaling 1 (SOCS1) expression in two in vitro fibrosis model systems and putatively shown to share CD63, an exosomal marker, as a binding partner in MMP-independent activities." (PMID 31765403, 2019).
gastric tumors (2 papers, 2004 to 2020). "Methylation of SOCS-1 was detected in 27.5% (11 of 40) of primary gastric tumours samples." (PMID 15354212, 2004). "In summary, hypermethylation of the promoter region of the SOCS-1 gene together with high production of endogenous IL6 and TGF-β leads to hyperactivation of JAK/STAT in gastric tumors." (PMID 33569347, 2020). "Nevertheless, in this study, we have demonstrated that SOCS-1 was silenced by hypermethylation in the AGS cell line and a subset of primary gastric tumour tissues." (PMID 15354212, 2004). "Moreover, methylation of SOCS-1 was detected in 27.5% (11 of 40) of primary gastric tumours samples, 10% (one of 10) of adjacent noncancer tissues but not in any (zero of nine) normal gastric mucosa." (PMID 15354212, 2004).
Granuloma (2 papers, 2017 to 2020). A compact, organized collection of mature mononuclear phagocytes, which may be but is not necessarily accompanied by accessory features such as necrosis. "SOCS1 has also been reported to be associated with caseous necrosis in granulomas from patients with TB lymphadenitis." (PMID 32373118, 2020). "Recent studies have indicated that SOCS-1 and -3 were higher in active TB patients than healthy subjects; the expression of SOCS-1 gene is associated with caseous necrosis in granulomas from patients with TB lymphadenitis." (PMID 28430824, 2017).
hepatitis C (2 papers, 2010 to 2014). "Furthermore, the cross-talk between PD-1 and the suppressor of cytokine signaling-1 negatively regulates IL-12 expression by limiting STAT1 phosphorylation in monocytes/macrophages from hepatitis C virus infection." (PMID 24853068, 2014). "Moreover, silenced SOCS1 expression due to CpG methylation is involved in pathogenesis of hepatitis C, HCC, and many other types of human cancers." (PMID 20862390, 2010). "In addition, SOCS1 gene methylation is also detected in patients with hepatitis C." (PMID 20862390, 2010).
Immunodeficiency (2 papers, 2015 to 2024). Failure of the immune system to protect the body adequately from infection, due to the absence or insufficiency of some component process or substance. "When analyzing gene expression of CLEC16A, DEXI and SOCS1 in whole blood from common variable immunodeficiency patients, higher level of CLEC16A expression was only observed in the AA group (homozygous for the protective allele) of rs17806056, also in partial LD with rs12708716 (r2 = 0.555)." (PMID 26203907, 2015).
infertile (2 papers, 2021 to 2023). "There was a tendency for redistribution of apical SOCS1 mRNA from the luminal epithelium in fertile women to the glandular epithelium of infertile women." (PMID 36572790, 2023). "It has been revealed that compared to fertile women, women with unexplained infertility have high endometrial levels of the inhibitor of LIF, SOCS1, accompanied by low levels of LIF receptor (LIFR) and gp130." (PMID 34496883, 2021). "It is likely that the function of SOCS1 and LIF are affected in these women with infertility, and these disturbances in the SOCS1 pathway could possibly explain the infertility of women with RIF." (PMID 34496883, 2021).
infiltrating ductal breast carcinoma (2 papers, 2003 to 2018). "In sections obtained from patients with infiltrating ductal breast carcinoma, gene expression of SOCS-1, -2, -3 and CIS was associated with the entire area of the tumour invasion." (PMID 12888825, 2003). "Consequently, we designed the current study to evaluate the expression of SOCS1–3 and SOCS5 genes in invasive ductal carcinoma of the breast compared with the corresponding adjacent non-cancerous tissues (ANCTs)." (PMID 30453988, 2018).
ischemia (2 papers, 2017 to 2025). A hypoperfusion of the BLOOD through an organ or tissue caused by a PATHOLOGIC CONSTRICTION or obstruction of its BLOOD VESSELS, or an absence of BLOOD CIRCULATION. "MiR-155 in macrophage-derived exosomes promoted tubular injury by inhibiting SOCS-1 expression in ischemia-induced AKI." (PMID 40308762, 2025). "HO-1 activator CoPP can reduce the expressions of TLR2, TLR4, IRAK-4 and TRAF6, and markedly increases the expressions of TLR negative regulators, such as SOCS-1, IRAK-M and SHIP-1, in ischemia/reperfusion liver injury in rat." (PMID 29057806, 2017).
leprosy (2 papers, 2013 to 2025). Leprosy is a chronic infectious disease affecting primarily the skin and peripheral nervous system. "SOCS1 known to be a regulator of Th17 differentiation also showed significantly increased expression (p<0.01) in the resistant form of leprosy and supported the increased activation of STAT3 in tuberculoid leprosy." (PMID 23936569, 2013). "In summary, it is evident that RORC was associated with IL-17+ cells and phosphorylated STAT3 rather than total STAT3 expression revealed functional differences in leprosy and was in agreement with the activation by SOCS1." (PMID 23936569, 2013).
lung disease (2 papers, 2021 to 2022). "Importantly, the gene silencing of SOCS1 in vivo completely reversed the protective effects of miR-122 inhibition on HRV-induced lung disease." (PMID 36142450, 2022). "In order to demonstrate unequivocally the mechanistic relevance of miR-122–SOCS1 target interaction in vivo for the expression of RV-induced lung disease, we treated mice with miR-122 antagomirs (or scrambled oligonucleotides) to increase the transcript levels of the miR-122 target SOCS1." (PMID 33830082, 2021). "Thus, miR-122 mediates its proinflammatory and antiviral effects in RV-induced lung disease at a posttranslational level via reduced SOCS1 in vivo." (PMID 33830082, 2021). "Importantly, gene silencing of SOCS1 in vivo completely reversed the protective effects of miR-122 inhibition on RV-induced lung disease." (PMID 33830082, 2021).
Lymphadenopathy (2 papers, 2020 to 2021). Enlargement (swelling) of a lymph node. "In addition, SOCS1-KIR administration reduced lymphadenopathy, severity of skin lesions, autoantibody production, and modestly reduced kidney pathology." (PMID 33737712, 2021). "Together, these results suggested that SOCS1-KIR treatment may reduce lymphadenopathy and splenomegaly in the MRL/lpr mouse." (PMID 33737712, 2021). "We next assessed SOCS1-KIR mitigation of lymphadenopathy using a larger sample size." (PMID 33737712, 2021). "We show that SOCS1-KIR administration diminished the accumulation of IFN-γ-producing memory T cells, lymphadenopathy, and cutaneous disease." (PMID 33737712, 2021). "Using a cohort of four SOCS1-KIR treated and four PBS control 8-week-old MRL/lpr mice, we initially assessed the effect of the SOCS1 mimetic peptide on lymphadenopathy." (PMID 33737712, 2021).
mastitis (2 papers, 2020 to 2022). Inflammation of breast tissue during lactation or postpartum due to an obstructed duct or infection. "The EV-miR-221/SOCS1/STAT1/STAT3 axis not only increases the proportion of M1-like macrophages in the early stage of mastitis but also provides a new direction for exploring the pathogenesis of mastitis." (PMID 35769456, 2022).
metabolic syndrome (2 papers, 2010 to 2016). A cluster of metabolic risk factors for CARDIOVASCULAR DISEASES and TYPE 2 DIABETES MELLITUS. "Lastly, two potentially protective genes, EGFR and SOCS1, were identified with iHS, which suggests that these genes may be undergoing recent selective sweeps associated with the high prevalence of metabolic syndrome in modern humans." (PMID 27444955, 2016). "Although it remains unclear whether SOCS1 polymorphisms modify SOCS1 expression in the liver and SOCS1 polymorphisms influence insulin sensitivity and lipid metabolism, SOCS1 polymorphisms might be associated with metabolic syndrome in humans." (PMID 20862390, 2010). "In contrast, it has been shown that an excessive induction of SOCS1 by TLR ligands and cytokines contributes to the alteration of insulin sensitivity in metabolic syndrome." (PMID 20862390, 2010).
metastatic melanoma (2 papers, 2010 to 2017). A melanoma that has spread from its primary site to another anatomic site. "The association of SOCS1 expression with PD-L1 further refine the selection of predictive biomarkers to anti-PD-1 based therapy, or therapies that induce antitumor immunity, in patients with metastatic melanoma." (PMID 28079159, 2017). "The baseline expression of SOCS1 and SOCS3 protein was measured in a panel of n = 10 human metastatic melanoma cell lines by immunoblot analysis." (PMID 20398276, 2010). "Subcutaneous injection of B16shR-SOCS1 cells in CD4 T-cell KO and WT mice promoted otherwise, a significant reduction of lung metastatic nodules, suggesting that SOCS1-silencing elicits a protective immune response against metastatic melanoma mediated by CD8+ T-cells." (PMID 28079159, 2017).
myeloid leukemia (2 papers, 2013 to 2024). A clonal proliferation of myeloid cells and their precursors in the bone marrow, peripheral blood, and spleen. "The human myeloid leukemia cell line TF-1 expresses endogenous SOCS-1 and GMR, and is dependent on GM-CSF for growth and survival." (PMID 24086733, 2013).
plasma cell disorders (2 papers, 2007 to 2008). "Slow-appearing plasma cell tumors expressed Socs1 and Socs2 but v-Abl-accelerated plasma cell tumors expressed 4–5 times as much." (PMID 17764563, 2007).
polycythemia vera (2 papers, 2016 to 2022). "Similarly, it has been reported that the histone deacetylase inhibitor vorinostat induces apoptosis by reactivation of SOCS1 and SOCS3 in polycythemia vera (PV)." (PMID 35611249, 2022).
primary immunodeficiencies (2 papers, 2020 to 2022). "SOCS1 (Suppressor of cytokine signaling 1) is part of negative-feedback signaling pathways downstream of cytokine receptors, including the interferon gamma receptor, that downregulates STAT-mediated signals, and a protein truncating mutation in SOCS1 was causally related to primary immunodeficiency." (PMID 36755664, 2022).
pulmonary TB (2 papers, 2015 to 2022). "While we could not detect SOCS-1 mRNA in PBMCs, confirming a previous report from our group, we report increased mRNA expression of SOCS-3 in PBMCs from pulmonary TB patients when compared to PBMCs from healthy controls." (PMID 25887604, 2015).
rectal cancer (2 papers, 2014 to 2019). A primary or metastatic malignant neoplasm that affects the rectum. "In 2012, Jo and colleagues used methylation specific PCR to examine a panel of 5 CIMP markers (i.e., CACNA1G, IGF2, NEUROG1, RUNX3, and SOCS1) in rectal cancer patients receiving 5-FU-based neoadjuvant chemoradiation." (PMID 31390840, 2019). "Several cytokines, including interleukins and interferons, and other mediators of inflammation were associated with both colon (INFGR1, IL6, IRF2, NFκB1A, TLR2) and rectal cancer survival (IL1A and IL3), as was suppressor of cytokine signaling (SOCS1)." (PMID 25541970, 2014).
renal cell carcinoma (2 papers, 2022 to 2025). "In renal cell carcinoma, RNF7 activates the JAK/STAT3 signaling pathway by inducing SOCS1 ubiquitination, leading to reduced cellular apoptosis." (PMID 40251202, 2025).
sacroiliitis (2 papers, 2017 to 2023). "In patients with ankylosing spondylitis, methylation of SOCS-1 significantly associated with severity of patient's spondylopathy, sacroiliitis and acute phase reactant CRP." (PMID 28915645, 2017).
Sézary syndrome (2 papers, 2023 to 2024). "In PCTFHL no 3 in particular, the clinical presentation as erythematosquamous plaques, the presence of epidermotropism, and the SOCS1 mutation may have suggested the diagnosis of MF or Sezary syndrome." (PMID 37081015, 2023).